LAMP2 (lysosome associated membrane protein 2)
Diseases named in the same sentence as LAMP2 in open-access papers (continued):
Sharing a sentence is not in itself a finding about the gene and the disease.
demyelinating disease (1 paper, 2023). A broad group of disorders that affect the myelin sheaths that cover the neurons. "Prior investigations linked IGFBP7 and LAMP2 to demyelinating disease or MS, while the underlying mechanism remained unknown." (PMID 37174963, 2023).
depression (1 paper, 2022). "In particular, we discovered for the first time that RAB1A, GNAI3, RAB33B, LAMP2, and KIF5B might be potential markers for the diagnosis of depression." (PMID 35559009, 2022).
disc degeneration (1 paper, 2020). "In our western blot analysis, LAMP2 significantly increased progressively with increasing disc degeneration grade." (PMID 31802633, 2020). "LAMP2 rose with increasing disc degeneration grade through grade V. In the quantitative analysis of colocalization, grade III is significantly higher than grade II and V (P < 0.05)." (PMID 31802633, 2020).
endometrial cancer (1 paper, 2023). Primary or metastatic malignant neoplasm involving the endometrium (mucous membrane that lines the endometrial cavity). "The incorporation of RTN4, LAMP2, WDR1, KRT13, ALDH2 and ILF3 gave rise to a ten-marker biomarker panel, which predicted endometrial cancer with an AUC of 0.91 (0.86–0.96), and was the best performing diagnostic model." (PMID 36807337, 2023).
endometriosis (1 paper, 2022). The growth of functional endometrial tissue in anatomic sites outside the uterine body. "Our results also revealed that cluster genes and proteins in autophagy (BECN1 and LAMP2) significantly increased in association with an increased level of palmitic acid and the ceramide synthesis gene in CCs under the pathological condition of endometriosis." (PMID 35992117, 2022).
Hunter syndrome (1 paper, 2010). "In contrast to the vast majority of lysosomal storage disorders, which are inherited in an autosomal recessive manner, FD, together with mucopolysaccharidosis type II (Hunter syndrome) and Danon disease (LAMP2 deficiency), is inherited as an X-linked trait." (PMID 21092187, 2010).
hyperandrogenism (1 paper, 2025). Excessive secretion of androgens from the adrenal glands or gonads. "The proteins IGFBP5, LAMP2, and CDH5 may contribute to the mechanisms underlying the adverse effects of hyperandrogenism on oocyte quality in PCOS patients." (PMID 40444232, 2025). "In summary, IGFBP5, LAMP2, and CDH5 may be involved in the process by which hyperandrogenism affects oocyte quality in PCOS patients." (PMID 40444232, 2025).
hypoxia (1 paper, 2015). A decrease in the amount of oxygen in the body. "Previous studies have demonstrated an increase in the expression of Hsc70, LAMP-2, and Hsp90 mRNAs, the proteins function together to remove protein aggregates and block neuronal apoptosis at 48 h after CI or cerebral hypoxia." (PMID 26042033, 2015).
injury (1 paper, 2021). Damage inflicted on the body as the direct or indirect result of an external force, with or without disruption of structural continuity. "Supplementation with rapamycin to alcohol-fed mice attenuated mTORC1 activation and ER stress, restored LAMP2 protein, and improved autophagy, leading to amelioration of alcohol-induced liver injury." (PMID 34685712, 2021).
invasive ductal carcinoma (1 paper, 2015). "Increased LAMP2 expression correlated with increased tumour progression from DCIS to invasive ductal carcinoma." (PMID 26658462, 2015).
Kawasaki disease (1 paper, 2023). A rare inflammatory disease characterized by an acute febrile, systemic, self-limiting, medium-vessel vasculitis primarily affecting children. "ATG16L1 0.42 (0.34, 0.50) vs. 0.49 (0.41,0.61), BECN1 0.46 (0.41, 0.63) vs. 0.83 (0.66,1), LC3II 0.41 ± 0.21 vs. 0.71 ± 0.19 were significantly downregulated in the IVIG-resistant Kawasaki disease group(P < 0.05), and LAMP2, p62 were not significantly different." (PMID 38114939, 2023).
left ventricular hypertrophy (1 paper, 2025). Enlargement of the LEFT VENTRICLE of the heart. "This case represents the youngest reported patient with a novel lysosome-associated membrane protein-2 variant, presenting with unexplained elevation of cardiac biomarkers, electrical abnormalities, and septal-predominant LGE on CMR, notably without left ventricular hypertrophy or dilation." (PMID 41394435, 2025).
leukemia (1 paper, 2022). A malignant (clonal) hematologic disorder, involving hematopoietic stem cells and characterized by the presence of primitive or atypical myeloid or lymphoid cells in the bone marrow and the blood. "As expected, genes associated with AML proliferation (FLT3, KIT), leukemia stem cells (CD34, CD38, and IL1RAP), and candidate genes overexpressed in AML (CD99, CD200, and LAMP2) were downregulated after chemotherapy, consistent with recent scRNA-Seq and immunohistochemistry data." (PMID 36099049, 2022).
lung adenocarcinoma (1 paper, 2015). A carcinoma that arises from the lung and is characterized by the presence of malignant glandular epithelial cells. "The formation of the enlarged LAMP2 particles due to E2F1 depletion was also found in human lung adenocarcinoma cell line A549, suggesting that such phenomenon is not cell type-specific." (PMID 26356814, 2015).
metastatic tumors (1 paper, 2020). "In metastatic tumors found in the lungs of such mice, LAMP2 expression was decreased in mice with FAM215A-knockdown cell-derived tumors compared to mice injected with control cells." (PMID 32295144, 2020).
multiple sclerosis (1 paper, 2024). A progressive autoimmune disorder affecting the central nervous system resulting in demyelination. "This study identified IREB2, LAMP2, ISCU, ATP6V1G1, ATP13A2, and SKP1 as genes associated with multiple sclerosis (MS) and iron metabolism, establishing their multi-gene diagnostic value for MS with an AUC of 0.83." (PMID 38590521, 2024).
myeloid leukemia (1 paper, 2021). A clonal proliferation of myeloid cells and their precursors in the bone marrow, peripheral blood, and spleen. "Myeloid leukemia cells transfected with miR-15a-5p inhibitor revealed increased amounts of LC3-II and LAMP-2 detected by Western blotting and immunofluorescence and a decreased protein level of p62/SQSTM1 relative to the scrambled condition." (PMID 34068078, 2021).
myositis (1 paper, 2025). "Interestingly, LAMP2 and LC3 expression in the anti-Ku-positive group tended to be the highest, suggesting that lysosomal degradation disorders may contribute to anti-Ku-associated myositis, distinguishing it from sIBM." (PMID 40599787, 2025).
nephrolithiasis (1 paper, 2024). The presence of a calculus in the pelvis of the kidney; this is most often composed of mineral salts and proteins. "In addition, GSVA results revealed that cluster 1 with higher expression of LAMP2 and MDM4, was enriched in lipid metabolism, amino acid metabolism, bile acid metabolism, and else, which can affect the risk of nephrolithiasis." (PMID 38536018, 2024). "Moreover, we partitioned a set of 29 nephrolithiasis samples into two distinct clusters based on the expression levels of LAMP2 and MDM4." (PMID 38536018, 2024).
osteoporosis (1 paper, 2022). A condition of reduced bone mass, with decreased cortical thickness and a decrease in the number and size of the trabeculae of cancellous bone (but normal chemical composition), resulting in increased fracture incidence. "We ultimately identified 4 core proteins (GSTP1, LAMP2, COPB1, RAB5B) that were significantly differentially expressed in the bone of osteoporosis patients with iron accumulation, and validated the changed protein level in the serum of the medical examination population." (PMID 36313751, 2022). "Finally, we screened four candidate proteins of osteoporosis with iron accumulation, GSTP1, LAMP2, COPB1, and RAB5B." (PMID 36313751, 2022). "Together, these 4 core proteins (GSTP1, LAMP2, COPB1, and RAB5B) may account for osteoporosis with iron accumulation, and potentially be a serum marker for it." (PMID 36313751, 2022). "The relationship between LAMP2 and osteoporosis has not been examined." (PMID 36313751, 2022). "Therefore, we speculate that these 4 DEPs (GSTP1, LAMP2, COPB1, RAB5B) may be novel candidate core proteins of osteoporosis with iron accumulation." (PMID 36313751, 2022).
pancreatic neuroendocrine tumor (1 paper, 2019). Pancreatic endocrine tumor, also known as pancreatic neuroendocrine tumor (PNET), describes a group of endocrine tumors originating in the pancreas that are usually indolent and benign, but may have the potential to be malignant. "The lysosome-associated membrane protein-2 (LAMP-2) is associated with endocytosis, knockdown of LAMP-2 improved the therapeutic effect of sunitinib in pancreatic neuroendocrine tumors." (PMID 31447954, 2019).
parasitic infection (1 paper, 2012). "Previous studies had shown that parasitic infection with Nb induced the expression of AAM genes in Mac3+ macrophages in the lung suggesting that Mac3 (also known as CD107b and lysosomal-associated membrane protein 2, LAMP2) may also be induced by IL-4 and IL-13." (PMID 22292924, 2012).
Paroxysmal supraventricular tachycardia (1 paper, 2026). An episodic form of supraventricular tachycardia with abrupt onset and termination. "Intron 6 is a well-documented mutation hotspot in the LAMP2 gene: IVS6 + 5G > C causes HCM with paroxysmal supraventricular tachycardia, while IVS6 + 1G > T (Case 1) induces similar HCM/WPW but allows partial normal splicing, enabling posttransplant survival." (PMID 41560058, 2026).
prion disease (1 paper, 2012). A transmissible disease that is caused by a protein that is able to induce abnormal folding of normal cellular proteins, leading to characteristic spongiform brain changes, which are associated with neuronal loss without an inflammatory response. "Galectin-3 knockout mice express low levels of lysosomal activation marker (LAMP-2) and autophagy markers, suggesting that endosomal/lysosomal dysfunction in combination with reduced autophagy may contribute to the development of prion diseases." (PMID 22897917, 2012).
pulmonary fibrosis (1 paper, 2022). Chronic progressive interstitial lung disorder characterized by the replacement of the lung tissue by connective tissue, leading to progressive dyspnea, respiratory failure, or right heart failure. "Beclin1, LC3B, LAMP2, TGF-ß, and MLPH were up-regulated induced by CDP, promoting autophagy and pulmonary fibrosis." (PMID 35057792, 2022).
retinal degeneration (1 paper, 2025). Degeneration of the retina. "Retinal degeneration in Lamp2−/− mice is mainly attributed to the rapid degeneration of the RPE, whereby they show signs of altered proteostasis and progressive accumulation of extracellular material in the subretinal space." (PMID 41168502, 2025).
rhabdomyosarcoma (1 paper, 2013). A rare aggressive malignant mesenchymal neoplasm arising from skeletal muscle. "The assay was performed using human rhabdomyosarcoma (RD) cells, as several mouse-specific LAMP2 antibodies produced a high background signal in COP-5 cells." (PMID 24039580, 2013).
Salmonella Infections (1 paper, 2008). Infections with bacteria of the genus SALMONELLA. "In order to determine the relative importance of LAMP-1 and LAMP-2 to Salmonella infection, we used RNAi to knockdown levels of these proteins in cells." (PMID 18958159, 2008).
sarcoma (1 paper, 2021). A usually aggressive malignant neoplasm of the soft tissue or bone. "Lipid accumulation was also detected in sarcoma tissues in close proximity to tumor area that express the acid-related biomarker LAMP2." (PMID 33467731, 2021).
silicosis (1 paper, 2025). Silicosis is a respiratory disease caused by breathing in (inhaling) silica dust. "However, the level of LAMP2 in silica-stimulated mouse fibroblasts showed a completely opposite trend compared to that in the lung tissue of silicosis mice." (PMID 41378210, 2025).
steatosis (1 paper, 2024). Increased lipid within the cytoplasm of cells. "Clofibrate significantly inhibited HFD-induced steatosis, increasing p62-, LAMP2-, and Pex5-positive granules by 7.5-, 7.2-, and 71.4-fold, respectively, while decreasing NBR1 expression." (PMID 39765694, 2024). "The results suggest that steatosis was completely suppressed through peroxisome activation; however, an imbalance between the induction and inhibition of pexophagy was demonstrated by increased levels of p62, LAMP2, and Pex5." (PMID 39765694, 2024).
ventricular fibrillation (1 paper, 2020). A disorder characterized by an electrocardiographic finding of a rapid grossly irregular ventricular rhythm with marked variability in QRS cycle length, morphology, and amplitude. "After 2 episodes of ventricular fibrillation within 2 years, genetic testing identified a novel LAMP2 pathogenic variant." (PMID 32248794, 2020).
ZIKV infection (1 paper, 2022). "To test whether ZIKV infection promotes fusion of LDs with lysosomes, we assessed whether LDs co-localized with lysosome-associated membrane protein 2 (LAMP2), via confocal microscopy." (PMID 36405969, 2022). "We next assessed whether LDs co-localized with LAMP2 in cells transfected with siNC or siAMPK followed by ZIKV infection." (PMID 36405969, 2022).
Zinc deficiency (1 paper, 2024). A deficiency of the essential metal Zinc; an essential cofactor for many enzymes. "Furthermore, we noted a significant decrease in the expression level of lysosome-associated membrane protein 2 (LAMP 2), which suggested that zinc deficiency inhibited the formation of autophagosome in ovary." (PMID 38807213, 2024).
cancer (60 papers, 2009 to 2025). A tumor composed of atypical neoplastic, often pleomorphic cells that invade other tissues. "Although LAMP2 is also a well-recognized EV marker associated with cancer, we observed slight significance for differentiating between PDAC and healthy group." (PMID 40598203, 2025). "Expression of LAMP1 and LAMP2, the most abundant lysosomal membrane proteins, has been shown to be either upregulated or downregulated in cancer and associated with chemoresistance." (PMID 41381430, 2025). "In the last decades, several reports have shown that lysosomal membrane proteins, such as the lysosome-associated membrane proteins 1 and 2 (LAMP1 and LAMP2), are deregulated in different cancer types and their expression has been correlated to drug efficacy." (PMID 41381430, 2025). "LAMP2 (lysosome-associated membrane protein 2) plays a crucial role in helping cancer cells survive in acidic environments." (PMID 39404428, 2024). "An increased expression of LAMP2 in salivary adenoid cystic carcinoma, which was associated with cancer progression." (PMID 38240686, 2024). "Elevated LAMP2 levels in neuroblastoma upregulated autophagy and caused apoptosis, reflecting the diverse outcomes of increased autophagy in cancer settings." (PMID 35806209, 2022). "We also found the protein expression of LAMP2 across a pan-cancer subtype; high LAMP2 protein expression was associated with the k3 subtype of the innate immune system." (PMID 35530327, 2022). "The results showed an increased expression of LAMP2 in salivary adenoid cystic carcinoma, which was associated with cancer progression." (PMID 33718194, 2021). "At the same time, FAM215A improves the ability of LAMP2, which plays an important role in the process of autophagy, and also seems to imply a new treatment strategy to overcome the failure of anti-cancer drug treatment caused by autophagy." (PMID 32295144, 2020). "In the last decades, several reports have shown that lysosomal membrane proteins, particularly lysosome-associated membrane proteins (LAMPs) 1 and 2 (LAMP1 and LAMP2), are deregulated in different cancer types and their expression has been associated with drug resistance." (PMID 41381430, 2025). "LAMP2 has been linked to different cancer relevant processes in different entities." (PMID 38802361, 2024). "ROC curves were constructed to assess the diagnostic value of LAMP2 in other cancers." (PMID 35530327, 2022). "The LAMP2 gene encodes a lysosomal membrane protein involved in chaperone-dependent autophagy; increasing levels of this gene’s expression are seen in the early stages of cancer." (PMID 33322704, 2020). "Many reports show that LAMP1 and LAMP2 are implicated in promoting cancer progression." (PMID 31425520, 2019). "Two homologs of LAMP3, LAMP1 and LAMP2, have been associated with cancer metastasis previously." (PMID 23294542, 2013). "Analysis of biochemical changes caused by PIKfyve kinase inhibitors reveals that resistant cancer cells contain higher level of p38MAPK protein and phosphorylation, which subsequently results in phosphorylation of lysosomal-associated membrane protein 2 (LAMP2) and compensatory autophagy function." (PMID 36646695, 2023). "Hence, the studies focusing on a unique molecular subtype or immune subtype may help determine the potential mechanism of action of LAMP2 and demonstrate that LAMP2 is a promising diagnostic pan-cancer biomarker that is involved in immune regulation." (PMID 35530327, 2022). "Initially, we ranked the cell lines present in the CRISPR KO screening according to their LAMP2 expression, using gene expression data included in the Cancer Cell Line Encyclopedia (CCLE)." (PMID 41381430, 2025). "Inhibition of LAMP-2 reverses macrophage activation, increases tumor cytotoxicity, and inhibits cancer progression." (PMID 40277899, 2025).